SNRNP200 (small nuclear ribonucleoprotein U5 subunit 200)
Description:
Catalyzes the ATP-dependent unwinding of U4/U6 RNA duplices, an essential step in the assembly of a catalytically active spliceosome. Plays a role in pre-mRNA splicing as a core component of precatalytic, catalytic and postcatalytic spliceosomal complexes. As a component of the minor spliceosome, involved in the splicing of U12-type introns in pre-mRNAs (Probable). Involved in spliceosome assembly, activation and disassembly. Mediates changes in the dynamic network of RNA-RNA interactions in the spliceosome.
Synonyms: U5-200KD; ASCC3L1; BRR2; HELIC2; KIAA0788; RP33
Tractability: Small molecule: a structure with a bound ligand is known; a high-quality ligand is known. Antibody: its Gene Ontology location is reachable by antibodies, with high confidence. PROTAC: UniProt records ubiquitination sites on it; ubiquitination databases record sites on it; its protein half-life has been measured; a small molecule that binds it is known.
Target class: Enzyme; Hydrolase
Chemical probes: TP-061 (high quality), TP-061
Gene: Protein-coding gene on chromosome 2 (96,274,338 to 96,321,271, reverse strand). Ensembl gene ENSG00000144028.
Subcellular location: Nucleus
Subcellular location (Human Protein Atlas): Nucleoplasm; Cytosol; Primary cilium
Pathways (Reactome):
Metabolism of RNA: mRNA Splicing - Major Pathway; mRNA Splicing - Minor Pathway
Disease: Dengue Virus-Host Interactions
Gene Ontology:
Molecular function: ATP hydrolysis activity; helicase activity; identical protein binding; protein binding; RNA binding; RNA helicase activity; ATP binding; nucleic acid binding
Biological process: mRNA splicing, via spliceosome; osteoblast differentiation; spliceosome conformational change to release U4 (or U4atac) and U1 (or U11); cis assembly of pre-catalytic spliceosome; negative regulation of mRNA splicing, via spliceosome; spliceosomal snRNP assembly; spliceosomal tri-snRNP complex assembly
Cellular component: catalytic step 2 spliceosome; membrane; nucleoplasm; nucleus; post-spliceosomal complex; precatalytic spliceosome; spliceosomal complex; U12-type catalytic step 2 spliceosome; U12-type precatalytic spliceosome; U2-type catalytic step 1 spliceosome; U2-type catalytic step 2 spliceosome; U2-type precatalytic spliceosome; U4/U6 x U5 tri-snRNP complex; U5 snRNP; U4atac/U6atac x U5 tri-snRNP complex; small nuclear ribonucleoprotein complex
Genetic constraint (gnomAD): Loss-of-function variants: 65 observed, 255.98 expected, observed/expected ratio (o/e) 0.25, 90% interval 0.21 to 0.31. The upper end of that interval is the gene's LOEUF score, 0.31, which puts it in group 1 of 6, group 1 being the genes least tolerant of losing a copy. Missense variants: 1,570 observed, 2,851.9 expected, observed/expected ratio (o/e) 0.55, 90% interval 0.53 to 0.57. Synonymous variants: 934 observed, 1,075.6 expected, observed/expected ratio (o/e) 0.87, 90% interval 0.82 to 0.92.
Homologues: Orthologues: chimpanzee SNRNP200 (100% identical), macaque SNRNP200 (99% identical), dog SNRNP200 (99% identical), rabbit SNRNP200 (99% identical), rat Snrnp200 (99% identical), guinea pig SNRNP200 (99% identical), pig SNRNP200 (99% identical), mouse Snrnp200 (99% identical), tropical clawed frog snrnp200 (94% identical), zebrafish snrnp200 (90% identical), Drosophila melanogaster Brr2 (75% identical). Paralogues in human: ASCC3 (40% identical), HFM1 (16% identical), POLQ (13% identical), DDX60L (9% identical), HELQ (9% identical), DDX60 (8% identical), SKIC2 (8% identical), MTREX (7% identical).